NRG1 (neuregulin 1)
Diseases named in the same sentence as NRG1 in open-access papers (continued):
Sharing a sentence is not in itself a finding about the gene and the disease.
tumor (continued). "One potential explanation for this conundrum is that the basal level of stimulation provided by tumor cell-derived NRG1 is sufficient to maximally drive the phosphorylation of these proteins." (PMID 31291965, 2019). "Further, the Erbb4-null tumor cells are still NRG1-responsive, as demonstrated by our phosphorylation-specific antibody array experiments." (PMID 31291965, 2019). "The expression of NRG1 from the intact copy of the gene, however, was detectable by IHC in patient's tumor." (PMID 30499260, 2019). "We provide evidence that the allosteric non-NRG1 competing modulator 9F7-F11, sensitizes tumor cells to caspase-mediated apoptosis through ITCH-dependent degradation of c-FLIP, and independently of ligand addiction." (PMID 31443721, 2019). "This property translated in vivo into an efficient anti-tumor activity in NRG1-addicted and NRG1-rearranged cancer cells, making it a first-in-class antibody." (PMID 31443721, 2019). "This led to a model for macrophage-enhanced iTEM in which NRG1 produced by tumor cells binds to ErbB3 on macrophages and induces expression of JAG1, which in turn enhances tumor cell intravasation." (PMID 29636067, 2018). "Taken as a whole, our data suggest that NRG1 in tumor cells, and ErbB3 and JAG1 in macrophages can play an important role in the metastatic cascade." (PMID 29636067, 2018). "Doxycycline treatment did not affect the growth rate of tumors, but there was a significant decrease in the number of circulating tumor cells in mice containing tumors with the NRG1 shRNA construct, which were fed the diet containing doxycycline." (PMID 29636067, 2018). "This study demonstrates that stimulation of macrophages by tumor cell NRG1 can enhance transendothelial migration and intravasation." (PMID 29636067, 2018). "While testing the efficacy of these antibodies in in vivo tumor models, we noticed that mice treated with anti-NRG1 exhibited hyperactivity and tremor." (PMID 29844389, 2018). "All adenocarcinomas with the NRG1 fusions showed an increased expression of pErbB3 in tumor cells compared to the adjacent normal bronchial epithelium in which a basal level staining of the protein was demonstrated." (PMID 29515761, 2018). "And a reverse relationship between miR-296-5p and NRG1 levels was observed in tumor tissues of HCC patients (P = 0.003, R = − 0.308)." (PMID 30486894, 2018). "We found that reducing NRG1 in the tumor cells reduced the ability of macrophages to stimulate iTEM, consistent with a model where NRG1 produced by tumor cells stimulates macrophages through ErbB3." (PMID 29636067, 2018). "Since the major source of the ErbB3 ligand NRG1 in the cell types we used was the tumor cells, we evaluated the effect of suppressing NRG1 expression in tumor cells." (PMID 29636067, 2018). "The aim of this study was to determine the role of NRG1, a ligand of the ErbB3 receptor, in macrophage stimulation of tumor cell transendothelial migration and intravasation." (PMID 29636067, 2018). "So, we expected to obtain a positive IHC results using an antibody against pErbB3 in tissue tumor samples where a functional NRG1 rearrangement occurs." (PMID 29515761, 2018). "In the studies reported here, we identified a novel paracrine loop for intravasation, in which NRG1 production by tumor cells stimulates macrophages to produce JAG1, resulting in increased transendothelial migration." (PMID 29636067, 2018). "In this paper, we identify a novel paracrine loop between tumor cells and macrophages involving neuregulin (NRG1) and notch signaling." (PMID 29636067, 2018). "Injecting the tumor cells into the mammary fat pads of mice to form a primary tumor indicated that suppression of NRG1 expression also reduced intravasation in vivo." (PMID 29636067, 2018). "Interrogation of BRD4-amplified HGSOC TCGA data revealed an enriched ERBB2 signature, consistent with activated NRG1 signaling in this tumor subset." (PMID 30036377, 2018).
tumor (continued). "Using qRT-PCR, we saw that there was very little NRG1 messenger (m)RNA expression in the macrophages, while high levels of mRNA were present in the tumor cells and endothelial cells." (PMID 29636067, 2018). "An in vitro transendothelial migration (iTEM) assay was used to examine the effects of short hairpin (sh)RNA targeting NRG1 in tumor cells and clustered regularly interspaced short palindromic repeats (CRISPR) knockout of jagged 1 (JAG1) in macrophages." (PMID 29636067, 2018). "In summary, NRG1 was most highly expressed by the tumor cells, while the receptor ErbB3 was mainly present on the surface of macrophages." (PMID 29636067, 2018). "The cells containing the control vector showed the expected increase in crossing the endothelial cell layer when macrophages were added, but this effect was significantly reduced for the NRG1 shRNA-expressing tumor cells." (PMID 29636067, 2018). "TCGA data analysis revealed that NRG1 is overexpressed in HNSCC with a prevalence of 45% (N = 228 tumor samples), where overexpression is defined as a 4-fold increase in mRNA levels over the median value across all samples (tumor samples and normal tissue)." (PMID 28723928, 2017). "Using the VeraTag proximity-based immunoassay we observed widespread ErbB3 protein (H3T) expression in the same patient tumor cohort analyzed for NRG1." (PMID 28723928, 2017). "We further investigated NRG1 expression in two HNSCC tumor microarrays from 46 patient samples using a quantitative RNA-based in-situ hybridization assay (QISH) with a probe that recognizes the NRG1β isoform." (PMID 28723928, 2017). "To evaluate the role of NRG1 as a predictive biomarker for KTN3379 response in HNSCC, we evaluated KTN3379 in vivo anti-tumor activity in a panel of NRG1-positive and NRG1-negative xenograft models, where NRG1 expression was determined by QISH." (PMID 28723928, 2017). "NRG1 expression is also a predictive biomarker for response to anti-HER3 therapy in human tumor xenograft models, including breast, head and neck, and esophageal cancers." (PMID 28899363, 2017). "Nevertheless, NRG1 expression in both HPV-positive and PI3K-mutated subsets was still high relative to most other tumor types)." (PMID 28723928, 2017). "We performed the same protocol in A17LKO mice founding a significant protective effect on tumor number and size compared with controls and a similar modulation of NRG1-ErbB4 signaling observed in AlbT3." (PMID 28751722, 2017). "We found that HNSCC expressed the highest levels of NRG1 compared to all major tumor types (>29,000 samples) in agreement with previously published studies." (PMID 28723928, 2017). "Specific activity profiles allow predicting their effect on tumor growth, the potential development of drug resistance, and their interference with physiological NRG-1-induced ErbB signaling in the heart and other organs." (PMID 27596216, 2016). "Consistently, both the upregulation of ErbB3 mRNA and the concentration of NRG-1 in tumor predict trastuzumab drug resistance." (PMID 27596216, 2016). "In preclinical studies, pertuzumab was found to inhibit NRG1-induced growth and morphogenesis in vitro, and trigger rapid tumour regression in NRG1-dependent xenograft model." (PMID 25691057, 2015). "We have identified candidate gene expression (TGFa, PECAM1, and NRG1) in tumor for the prediction of sorafenib response and PFS by RNA sequencing." (PMID 26046304, 2015). "AV-203 also shows potent tumor growth inhibition in a number of xenograft models where HER3 is activated by ligand NRG1 or HER2 overexpression." (PMID 25400118, 2014). "Recently, a novel study generated mAbs directed against NRG1 that demonstrated potent anti-tumor effects in combination with chemotherapy in NSCLC models, and prevented the expansion of residual tumor cells post chemotherapy regimes." (PMID 25344208, 2014). "Correlations of HER-receptors and NRG1 with estrogen levels in normal tissue, tumour tissue and plasma." (PMID 23991224, 2013).
tumor (continued). "In ER+ tumours from postmenopausal women, NRG1 levels correlated positively with EGFR/HER1 (r=0.606, P=0.002) and negatively to ESR1 (r=-0.769, P=0.003) and E2 levels (r=-0.542, P=0.020)." (PMID 23991224, 2013). "Among the growth factors susceptible to shedding by ADAM17, neuregulin-1 was the only candidate to mediate the effects of ADAM17 on MC38CEA motility and tumor angiogenesis." (PMID 23251384, 2012). "NRG1 maps to chromosome arm 8p, a region of common genomic alteration in human tumours including bladder." (PMID 21364580, 2011). "We have identified the consistent expression of NRG-1 by CAF in the tumour microenvironment and have thoroughly demonstrated that this ligand promotes tumourigenesis through ErbB3/PI3K/AKT activation." (PMID 21792199, 2011). "In this context, CAF-secreted NRG1 and tumor-cell HER3 form a key pro-tumor signaling axis." (PMID 41514658, 2025). "In our study, the serum NRG1, the NRG1 protein and mRNA in tumor tissue were detected." (PMID 40740239, 2025). "The ROC analysis makes it convincing that the serum NRG1, the protein and the mRNA levels of NRG1 in tumor tissue could predict the CRPC progression with high sensitivity and specificity." (PMID 40740239, 2025). "Given clinical data implicating NRG1 upregulation in poor outcomes on ADT, it is tempting to speculate that patients may benefit from pre-therapy selection by NRG1 immunohistochemistry on tumor specimens or by sNRG1 detection in the blood." (PMID 40740239, 2025). "Our integrated multi-omics analysis constructed the MPRS model to delineate CRC tumor ecology and identified NRG1 as a methylation biomarker with predicted phase-separation propensity, with potential therapeutic implications that warrant prospective validation." (PMID 41190067, 2025). "Our result showed that the soluble NRG1 from blood, and the NRG1 from tumor tissue were correlated to CRPC and could be used to predict the CRPC incidence." (PMID 40740239, 2025). "The result revealed that the serum NRG1 levels were positively correlated to NRG1 in biopsy tumor." (PMID 40740239, 2025). "Recent studies reveal that NRG1 play a pivotal role in tumorigenesis and tumor progression." (PMID 40959099, 2025). "Traditionally, paracrine growth factors were thought to be produced by cancer or neighboring stromal cells, but this study highlights tumor-infiltrating inflammatory cells as a dominant source of NRG1, emphasizing the therapeutic potential of targeting immune cell-derived signaling pathways." (PMID 41228234, 2025). "The present study investigated 3008 specimens from various tumor types to identify NRG1 fusions." (PMID 38173003, 2024). "In the case of NRG1 overexpression, the binding rate of NRG1 to HER3 (k8on) was identified as a significant parameter that impacts tumor growth, indicating that this physiological process could be an important therapeutic target for NRG1-overexpressing tumors." (PMID 38360930, 2024). "Moreover, in keeping with prior studies, those neoplasms with NRG1 fusions described here demonstrated low TMB." (PMID 39575425, 2024). "Notably, the incidence of NRG1 fusions is relatively low, with the largest published series using RNA-based sequencing detecting NRG1 fusions in only 41 out of 22,000 tumor specimens, resulting in an incidence of 0.2%." (PMID 38957319, 2024). "The experimental results of PDX models and in vitro cell lines were consistent, demonstrating that knocking down NRG1 or PI3K/AKT inhibition reduced tumor size, extended survival, slowed cell proliferation, increased apoptosis, reduced M2 macrophages, and increased neutrophils." (PMID 38331905, 2024). "Furthermore, zenocutuzumab (MCLA-128) can inhibit HER-2/HER-3 to mediate NRG1 signaling in tumor cells." (PMID 38705930, 2024). "In vitro, experiments have demonstrated that downregulation of NRG1 could inhibit the malignant behavior of tumor cells." (PMID 38331905, 2024). "Tumor microenvironment-derived NRG1 facilitates antiandrogen resistance in PCa." (PMID 38887275, 2024).
tumor (continued). "For NSCLC, recommendations comprised larotrectinib/entrectinib (unconventional SLC28A3::NTRK2 gene fusion), capmatinib (MET amplification, GCN: 16.7), afatinib (RBPMS::NRG1 gene fusion), and dabrafinib/trametinib in the case of a BRAF p.Val600Glu, and a non-V600E BRAF mutated tumor, respectively." (PMID 38136436, 2023). "Interestingly, high expression of stromal NRG1 was associated with improved survival in CRC cohorts, suggesting a tumor-suppressive function." (PMID 36912192, 2023). "Tumour cells themselves can also gain NRG1 alterations to promote progression." (PMID 36357571, 2023). "More recently, advances in cancer genomic sequencing have unravelled the molecular heterogeneity of PDAC and identified small patient subgroups harbouring unique actionable aberrations in BRCA, NTRK, NRG1 and mismatch repair genes paving the way to a more personalised approach for this tumour." (PMID 38550932, 2023). "Interestingly there was often a striking demarcation between NRG1+/pS6+ and pNDRG+ regions within a given tumor." (PMID 36944680, 2023). "Subsequent identification of ALK rearrangements and several cancer‐driver events, including ROS1, NRG1, NTRK1/RET fusion, BRAF (V600E) mutation, or MET amplification/Exon14 skipping, strengthened the concept of oncogene addiction and tumor heterogeneity as a pillar of modern cancer therapeutics." (PMID 35838331, 2022). "These recent eNRGy data suggest that zenocutuzumab may become the first targeted therapy for tumors with NRG1 fusions, either as a tumor-agnostic option for molecularly defined subtypes or for certain disease types." (PMID 36476337, 2022). "In addition, patients with mCRPC having increased tumor NRG1 activity showed an inferior response to second-generation antiandrogen therapy." (PMID 36176747, 2022). "NRG1 can activate HER3 to promote resistance in tumor cells." (PMID 35748788, 2022). "Paracrine growth factor–mediated resistance to TKI has previously been studied and, in some cases, may be attributed to tumor-intrinsic NRG1 overexpression invoked by oncogenic NRG1 genomic fusions." (PMID 34516823, 2021). "Moreover, the majority of HER3 was observed in differentiated squamous cells at the center of infiltrative tumor nests, while the NRG1 protein was mainly detected in the basaloid cells at the periphery of tumor islands." (PMID 34465724, 2021). "In addition, we observed that the majority of the HER3-positive cells were the differentiated cells in the center of the infiltrating tumor nests, and the NRG1-positive cells were primarily the basaloid cells at the periphery of the cell nests." (PMID 34465724, 2021). "Interestingly, NRG1 levels were heterogeneous among the different fibroblasts despite having been isolated from tumours of the same subtype." (PMID 33692466, 2021). "NRG1 was reported to act as an oncogene in various tumor development." (PMID 34531912, 2021). "The absence of NRG1 expression in tumours has also often been associated with DNA methylation at the CpG island around the transcription start site of NRG1." (PMID 34068503, 2021). "The safety and PK profile of seribantumab described here, combined with the demonstrated preclinical activity in tumor models with NRG1 fusions, support a tumor agnostic strategy for further development of seribantumab in patients with tumors driven by NRG1 fusions." (PMID 34250553, 2021). "Nrg1 derived from infiltrated dendritic cells in tumor microenvironment might be involved in neuropathic pain associated with cancers." (PMID 32434423, 2020). "In patients affected by PDAC, NRG1 fusions are detected only in KRAS wild-type tumors and usually in the absence of other concomitant driver gene mutations, suggesting that the rare NRG1 fusions act as an oncogenic driver in this tumor." (PMID 33115526, 2020).
tumor (continued). "NRG1 stimulates further NRG1 release in the tumor endothelium that may lead to an enhanced tumor protective effect whereas Herceptin, used in antibody treatment, works in an antagonistic fashion to NRG1." (PMID 30836676, 2019). "Finally, we demonstrate the effectiveness of co-targeting of BRD4 and NRG1 signaling in the context of BRD4-amplified patient-derived tumor models." (PMID 30036377, 2018). "To test whether inhibition of NRG1 signaling could result in anti-tumor activity in BRD4-amplified HGSOC tumors, we employed lapatinib, an orally available tyrosine kinase inhibitor with activity against the HER pathway." (PMID 30036377, 2018). "High tumor-expression of neuregulin 1 (NRG1), a ligand to HER3, may enhance sensitivity to duligotuzumab." (PMID 27843803, 2016). "Moreover, the trend toward elevated NRG1 expression and increased tumor shrinkage was observed in both study arms." (PMID 27843803, 2016). "Tumor samples were assayed for biomarkers [NRG1, ERBB3, and human papillomavirus (HPV) status]." (PMID 27843803, 2016). "However, autocrine signaling of NRG1-ErbB is observed in Schwann cell differentiation and remyelination or tumor growth." (PMID 26891847, 2016). "In this scenario, NRG-1 may advance tumor growth and/or promote tumor resistance during treatment with anti-ErbB2 therapies." (PMID 27596216, 2016). "In reciprocal manner, NRG-1, the most potent HER-3 ligand has been found to be released by tumor-associated stromal cells, further promoting the idea that the HER-3 activation is vital in sustaining tumor growth." (PMID 26590357, 2015). "The additive effect of the combination of lapatinib and pertuzumab on the inhibition of NRG1-stimulated HER signalling suggested that this combination might have improved anti-tumour activity." (PMID 25691057, 2015). "Although some studies have proposed that NRG1 may promote tumor growth, NRG1 has also been demonstrated to act as a principal tumor suppressor in many cancers." (PMID 26332771, 2015). "The explanation for this remains unclear, but this observation could be in accordance with previous data that indicate a possible tumor suppressor function of NRG1." (PMID 25992771, 2015). "Does ADAM17 contribute to MC38CEA tumor development through NRG-1 shedding?" (PMID 23251384, 2012). "There was considerable diversity in the expression of NRG1 in both cell lines and in tumours with higher expression of NRG1β than NRG1α, suggesting, as proposed previously, that the β-isoform may be more biologically important." (PMID 21364580, 2011). "Furthermore, we have demonstrated that CAF secretion of NRG-1 actively circumvents the inhibitory effect of erlotinib and promotes tumour growth providing an ‘escape’ mechanism to EGFR-targeted therapy." (PMID 21792199, 2011). "Our finding that NRG1 expression is higher in tumours of high grade and stage may be particularly relevant in this context, as these are tumours for which targeted therapies are most urgently needed." (PMID 21364580, 2011). "These genes are involved in the regulation of immune/inflammatory response (Lgals1, Ptgds, Tff2, Ubd), tumor angiogenesis (Lgals1, Esm1, Ndrg1), epidermal growth factor signaling (Erbb4, Nrg1), response to tissue injury (Tff2, Vnn1), and gene transcription (Id3, Ifrd1)." (PMID 19340302, 2009). "The role of NRG-1 in tumor invasion and metastasis is still unclear." (PMID 16901352, 2006). "Moreover, NRG1 in biopsy tumor was strongly correlated to the relative NRG1 mRNA levels in tumor." (PMID 40740239, 2025). "Additionally, ERBB3-targeting antibodies are now entering clinical trial for other indications (e.g. seribantumab for NRG1-fusion harboring tumours) (NCT04383210), which may provide further options for clinical investigation of this treatment concept." (PMID 35501832, 2022).